ACE (angiotensin I converting enzyme)
Diseases named in the same sentence as ACE in open-access papers (continued):
Sharing a sentence is not in itself a finding about the gene and the disease.
schizophrenia (25 papers, 2015 to 2025). A major psychotic disorder characterized by abnormalities in the perception or expression of reality. "Previous studies have suggested a potential association between ACE gene polymorphisms and psychiatric disorders, including schizophrenia." (PMID 41459362, 2025). "This study aimed to investigate the association between the ACE I/D polymorphism and schizophrenia in an Eastern Algerian population." (PMID 41459362, 2025). "This study aimed to investigate the association between the insertion/deletion (I/D) polymorphism in the ACE gene and schizophrenia in an Eastern Algerian population." (PMID 41459362, 2025). "In a Han Chinese population, an ACE gene insertion/deletion polymorphism was associated with schizophrenia risk and severity of depressive symptoms." (PMID 36173067, 2024). "The risk for schizophrenia was significantly higher in the ACE inhibitor group than in the ARB group (summary HR, 1.23 [95% CI, 1.05–1.43])." (PMID 38365637, 2024). "Although the use of ACE inhibitors was associated with an increased risk of schizophrenia compared with the use of ARB in the group aged > 45 years, the results were not consistent in the sensitivity analyses." (PMID 38365637, 2024). "For the primary outcome at ITT follow-up, the ACE inhibitor group showed a lower risk of schizophrenia occurrence than the thiazide group (summary HR 0.92 [95% CI, 0.86–0.99]; P =.02)." (PMID 38365637, 2024). "For the secondary outcome at ITT follow-up, the ACE inhibitor group exhibited a higher risk of schizophrenia occurrence than the ARB group (summary HR 1.27 [95% CI, 1.07–1.51]; P =.006)." (PMID 38365637, 2024). "In a Spanish population, the D allele of the ACE gene was a protective factor lowering the risk of developing schizophrenia by 50%." (PMID 36173067, 2024). "Specifically, low angiotensin-converting enzyme (ACE) messenger RNA and protein levels, which are targets of ACE inhibitors, are associated with an increased risk of schizophrenia." (PMID 38365637, 2024). "Although the differences between ACE inhibitors and thiazide diuretics were inconsistent, ACE inhibitors were consistently associated with a higher risk of schizophrenia than ARBs in both subgroup analyses and secondary outcomes." (PMID 38365637, 2024). "The potential association between ACE inhibitors and an increased risk of schizophrenia is highly relevant because of the number of affected patients and the burden of schizophrenia, warranting thorough investigation." (PMID 38365637, 2024). "Regarding mental and neurological diseases, ACE inhibitors were possibly related to a higher risk of schizophrenia in European and East Asian populations." (PMID 39567981, 2024). "The ACE inhibitor group showed a lower risk of schizophrenia occurrence than the thiazide group in only the total population (total population: calibrated HR 0.91 [95% CI, 0.85–0.98]; subgroup: calibrated HR 0.96 [95% CI, 0.88–1.04])." (PMID 38365637, 2024). "Given the widespread use of ACE inhibitors in hypertensive patients and their potential biological implications for schizophrenia risk, investigating this association using real-world data is essential." (PMID 38365637, 2024). "Genetic studies have identified an associationbetween the ACE I/D polymorphism (rs4646994) and schizophrenia; however, the findings arecontradictory." (PMID 35895876, 2023). "the capability of ACE to cleave peptidessuch as neurotensin and substance P, which are dysregulated in schizophrenia patients, theformer being associated with regulation of dopamine transmission and the latter withneuroinflammation." (PMID 35895876, 2023). "According to recent evidence, RAS and ACE appear to be linked to neurodegenerative diseases and schizophrenia, and reduced ACE levels have been found in patients with schizophrenia." (PMID 37371435, 2023).
schizophrenia (continued). "Although several studies reported that ACE activity is inconsistent in patients with schizophrenia, higher ACE activity is associated with cognitive dysfunction in patients with schizophrenia." (PMID 33315097, 2021). "Intriguingly, human genome/gene analysis on insertion/deletion (D) polymorphism in the angiotensin-converting enzyme (ACE) gene has indicated that the D allele is a protective factor against schizophrenia and chronic periodontitis." (PMID 31366073, 2019). "In the US results, the ACE inhibitor group showed a higher risk of schizophrenia occurrence than the ARB group, including the total population and the subgroup (total population: calibrated HR 1.21 [95% CI, 1.13–1.29]; subgroup: calibrated HR 1.18 [95% CI, 1.09–1.27])." (PMID 38365637, 2024). "However, the ACE inhibitor group showed a higher risk of schizophrenia occurrence than the ARB group (summary HR 1.23 [95% CI, 1.05–1.43]; P =.01, see eFigure 4 in Supplement 1)." (PMID 38365637, 2024). "However, the ACE inhibitor group showed a lower risk of schizophrenia occurrence than the thiazide group in only the total population (total population: calibrated HR 0.86 [95% CI, 0.75–0.99]; subgroup: calibrated HR 0.88 [95% CI, 0.73–1.06])." (PMID 38365637, 2024). "In the US results, the ACE inhibitor group showed a higher risk of schizophrenia occurrence than the ARB group, including the total population and the subgroup (total population: calibrated HR 1.29 [95% CI, 1.08–1.54]; subgroup: calibrated HR 1.24 [95% CI, 1.01–1.52])." (PMID 38365637, 2024). "The possible biological pathway for the association between ACE inhibitors and schizophrenia is that ACE and the central RAS may play a role in inflammation and immunity." (PMID 38365637, 2024). "Furthermore, through a summary-based Mendelianrandomization analysis, they showed an association of decreased ACE expression in bloodwith increased risk of schizophrenia." (PMID 35895876, 2023). "Specifically, we investigated whether the use of ACE inhibitors increased the risk of schizophrenia compared with the use of angiotensin receptor blockers (ARBs) or thiazide diuretics in the US and Korea across the Observational Health Data Sciences and Informatics (OHDSI) network." (PMID 38365637, 2024). "ACE and angiotensin II have been suggested to play important roles in brain dopaminergic neurotransmission; therefore, the ACE-I/D polymorphism has been investigated in schizophrenia etiology and clinical expression, as assessed using the Positive and Negative Syndrome Scale (PANSS)." (PMID 36293037, 2022). "Our recent studies suggested that the ACE gene is associated with a broad range of neurological diseases, including AD, amyotrophic lateral sclerosis, multiple sclerosis, Parkinson’s disease (PD), and schizophrenia, which is consistent with the findings from other groups." (PMID 34947975, 2021). "Elevated ACE levels have been found in the cerebrospinal fluid of patients with schizophrenia, while other studies reported decreased activity in specific brain regions, such as the basal ganglia in early-onset schizophrenia." (PMID 41459362, 2025). "Previous studies on the relationship between ACE inhibitors and schizophrenia have limitations in terms of sample size or cross-sectional design." (PMID 38365637, 2024). "In this study, we extensively estimated the comparative risks of ACE inhibitors and thiazide diuretics or ARBs on the occurrence of schizophrenia." (PMID 38365637, 2024). "We observed significantly lower prescriptions of beta-blockers and ACE inhibitors or ARBs in patients with schizophrenia." (PMID 37849318, 2023). "Abnormal levels of ACE in the cerebrospinal fluid (CSF) and plasma of patients with schizophrenia, have been previously reported." (PMID 33642980, 2021).
schizophrenia (continued). "An increased ACE activity in schizophrenia patients correlated positively with a significant increase in the serum levels of pro-inflammatory cytokines such as IL-17 and IFN-γ and cognitive deficits including disorganization of thought process." (PMID 28588507, 2017). "The etiological role of the schizophrenia candidate gene ACE was initially thought to relate to its involvement in dopamine metabolism." (PMID 29249829, 2017). "ACE activity is significantly increased in the plasma, CSF, and brains of schizophrenia patients compared with healthy controls." (PMID 28588507, 2017). "Among them, AGER (schizophrenia), CD40 (schizophrenia & bipolar), TNFRSF17 (schizophrenia), ACE (schizophrenia & Alzheimer’s) and SEPRING1 (schizophrenia) have drugs approved or in advanced clinical trials for several indications including cardiovascular and autoimmune conditions." (PMID 40281223, 2025). "Notably, ACE, which had Tier B evidence for both schizophrenia and Alzheimer’s, has approved drugs for cardiovascular indications." (PMID 40281223, 2025). "The possible explanation for the association of ACEIs with SCZ is that ACE and the central RAS could play a role in inflammation and immunity, and immune dysfunction might contribute to the pathogenesis of schizophrenia." (PMID 38166843, 2024). "Although RCT evidence is lacking, strong MR evidence suggests an association between ACE inhibitors and increased schizophrenia risk in both Europeans and East Asians, highlighting the need for greater pharmacovigilance." (PMID 39567981, 2024). "In conclusion, there was no explicit difference in the risk of schizophrenia between ACE inhibitors, ARBs, and thiazide diuretics across the two large databases in the US and South Korea." (PMID 38365637, 2024). "The risk of schizophrenia was not significantly different between the ACE inhibitor vs. ARB and ACE inhibitor vs. thiazide diuretic groups." (PMID 38365637, 2024). "Interestingly, we found ACE to be downregulated in schizophrenia for both sexes in the caudate nucleus." (PMID 38730231, 2024). "Consequently, prescription of beta-blockers and ACE inhibitors or ARBs was significantly lower in schizophrenia patients hospitalized with HF." (PMID 37849318, 2023). "Furthermore, prescriptions of beta-blockers and ACE inhibitors or ARBs were found to be lower in patients with schizophrenia." (PMID 37849318, 2023). "Indeed, that group had previously reported increased ACE activity in chronic schizophrenia patients compared to healthy controls, and suggested the potential of using combined ACE genotype and activity for predicting schizophrenia." (PMID 36293037, 2022). "The ACE gene is associated with a wide range of neurological diseases, including AD, amyotrophic lateral sclerosis (ALS), multiple sclerosis (MS), Parkinson’s disease (PD), and schizophrenia." (PMID 34947975, 2021). "Immune dysfunction due to reduced ACE activity may contribute to the development of schizophrenia." (PMID 38365637, 2024). "Thus, using drugs that modulate RAS, such as angiotensin 1 receptor (AT1) antagonists and angiotensin-converting enzyme (ACE) inhibitors, could help treat the neuroinflammatory processes underlying the pathogenesis of schizophrenia." (PMID 37371435, 2023). "Interestingly, the renin–angiotensin system (RAS) and angiotensin-converting enzyme (ACE), primarily involved in blood pressure regulation, appear to modulate PPARs and neuroinflammation and regulate GABAergic and dopaminergic neurotransmission, which are involved in schizophrenia." (PMID 37371435, 2023). "In schizophrenia (SCZ), higher angiotensin I-converting enzyme (ACE) levels have been reported in patient's blood and cerebrospinal fluid (CSF)." (PMID 26645626, 2015).
schizophrenia (continued). "After PS matching, the risk of schizophrenia was not significantly different among the groups (ACE inhibitor vs. ARB: summary hazard ratio [HR] 1.15 [95% confidence interval, CI, 0.99–1.33]; ACE inhibitor vs. thiazide diuretics: summary HR 0.91 [95% CI, 0.78–1.07])." (PMID 38365637, 2024).
osteoporosis (24 papers, 2008 to 2025). A condition of reduced bone mass, with decreased cortical thickness and a decrease in the number and size of the trabeculae of cancellous bone (but normal chemical composition), resulting in increased fracture incidence. "For example, females had an increased risk of developing ACE inhibitor-related coughing and osteoporosis due to prednisone, whereas males had a higher tendency to develop gynaecomastia when using spironolactone and erectile dysfunction from metoprolol." (PMID 36833654, 2023). "Numerous investigations reported that the local expression of RAS components such as renin, ACE-1, and AngII receptors in the skeletal system plays a vital role in local bone remodelling and participates in the progress of osteoporosis." (PMID 38200474, 2024). "A total of 27 target proteins were obtained, including CD31, EMCN, VEGF, AT1, AT2, ACE, and HIF-1a, all of which are involved in the pathological process of osteoporosis and bone loss and are the target proteins on which MQEP produces a marked effect." (PMID 36147560, 2022). "In the present analysis, some variants within three noteworthy candidates, which impinge upon endothelial function (eNOS, ACE and VEGFA), have shown significant impact on the risk of osteoporosis through different genetic models." (PMID 33499313, 2021). "Other prevalent PPOs were bone anti-resorptive or anabolic therapy in osteoporosis (13.1%) and the use of angiotensin converting enzyme (ACE) inhibitor with systolic heart failure (11.4%)." (PMID 27907210, 2016). "The hyperglycinemia noted in T2D is positively correlated with estrogen deficiency and the upregulation of the ACE/Ang II/AT1R axis and downregulation of the ACE2/Ang 1-7/Mas receptor axis and AT2R, which may promote osteoporosis." (PMID 37569338, 2023). "In conclusion, the present study has exposed three susceptible haplotypes (CTAAAT, ACDG and GATA) within eNOS, ACE and VEGFA genes, which manifest in multiplicative and dominant mode for inflicting endothelial-associated osteoporosis risk in postmenopausal women." (PMID 33499313, 2021). "Systemic and local RAAS is upregulated in T2D; hence, the ACE/Ang II/AT1R axis stimulates the activity of proinflammatory cytokines, resulting in increased osteoclastogenesis, reduced bone density and development of osteoporosis." (PMID 37569338, 2023). "Our findings suggested that SOX6, ACE, SYK and TGFB3 may play important roles in the bone formation of osteoporosis in postmenopausal women." (PMID 32496000, 2020). "T2D leads to upregulation of aldosterone and the ACE/Ang II/AT1R axis, potentially resulting in the parathyroid glands being over-stimulated and leading to increased PTH and 1,25-hydroxy vitamin D concentrations that could further lead to osteoporosis." (PMID 37569338, 2023). "Our previous finding indicated that abnormal histone acetylation of the ACE promoter mediated PDE‐induced osteogenic differentiation disorder in offspring, and confirmed that inhibition of ACE expression in the early postnatal period could effectively prevent and treat fetal‐originated osteoporosis." (PMID 40046408, 2025). "MAF of three SNPs of ACE gene i.e., rs1800764, rs1799752 and rs4343 were observed to be significantly dissimilar (p < 0.05), however MAF of rs4459609 was similar (p = 7.86) between women having osteoporosis and women without it." (PMID 33499313, 2021).
Hypoglycemia (23 papers, 2013 to 2025). A decreased concentration of glucose in the blood. "ACE inhibitors are responsible for temporarily increasing the sensitivity to insulin, leading to a higher risk of hypoglycemia when associated with sulphonylureas." (PMID 34946233, 2021). "Notably, although ACE inhibitors are generally safe medications, captopril was observed to be associated with hypoglycemia events when used in addition to DPP-4i′s." (PMID 34040513, 2021). "Another possible factor underlying hypoglycemia is concomitant therapy with ACE inhibitors." (PMID 32151247, 2020). "However, some other possible risk factors for hypoglycemia were recognized, including prolonged overnight fasting, physical activity, alcohol consumption, and concomitant therapy with ACE inhibitors." (PMID 32151247, 2020). "Many drugs have been reported as a cause of hypoglycemia, including quinine, beta blockers, and angiotensin-converting enzyme (ACE) inhibitors, as well as antidepressants such as selective serotonin reuptake inhibitors (SSRIs) and monoamine oxidase inhibitors (MAOIs)." (PMID 28148284, 2017). "The use of ACE inhibitors has been associated with increased insulin sensitivity in diabetic patients, and their concomitant use with antidiabetic therapies may facilitate their blood glucose-lowering effect with a concomitant risk of hypoglycemia." (PMID 32151247, 2020). "Low ACE activity is favourable for performance and hypoglycaemia awareness when substrate availability is limited, for example, during hypoglycaemia." (PMID 27347560, 2016). "The case reports regarding the use of ACE inhibitors in diabetic patients were followed by several case-control studies which documented the relationship between ACE inhibitior and hypoglycemia." (PMID 24072084, 2013). "Meanwhile, angiogenesis may be protected against by angiotensin-converting enzyme (ACE) inhibitors, and the inhibition of ACE activity might prevent or even reverse hypoglycemia-associated autonomic failure (HAAF)." (PMID 36230616, 2022). "Our study showed that sitagliptin use was associated with an increasedrisk of HHF in patients with T2DM receiving dialysis, especially in those withoutsevere hypoglycemia, without ACE inhibitors treatment, with prior HF or receivinghemodialysis." (PMID 27460913, 2016).
myocarditis (23 papers, 2018 to 2026). Myocarditis is a condition that is characterized by inflammation of the heart muscle (myocardium). "The association with ACE inhibitors and aspirin raises the question of whether these medications might influence the development of myocarditis or if they are merely reflective of pre‐existing cardiovascular conditions." (PMID 40401328, 2025). "First-line medications for the recovery phase of myocarditis to protect the myocardium are angiotensin-converting enzyme (ACE) inhibitors or angiotensin receptor blockers." (PMID 40091973, 2025). "This study provides evidence for a role for ACE inhibitors and beta blockers to prevent myocardial injury and scar deposition in in vivo models of myocarditis." (PMID 31673885, 2019). "Current guidelines favor symptomatic management of myocarditis with the use of diuretics, ACE inhibitors and beta blockers along with treatment of the offending agent where applicable." (PMID 30050613, 2018). "Improvement of cardiac dimensions and function in patients with acute myocarditis is common either in response to supportive measures (such as diuretics, ACE inhibitors, carvedilol, digitalis, gliflozins, etc.)and/or specific treatments, such as anti-viral and immunosuppressive agents." (PMID 39200277, 2024). "Overall, it appears ACE inhibitor and beta blocker treatment might have the broadest effectiveness in preventing the most clinically relevant outcomes of necrosis and fibrosis in experimental myocarditis." (PMID 31673885, 2019). "Prior angiotensin converting enzyme (ACE) inhibitor and aspirin use were more common among patients who developed myocarditis (50% vs. 17.5%, OR: 4.7, CI 1.3−16.9, p = 0.01; 55.5% vs. 15%, OR: 9.4, CI 2.21−29.67, p < 0.01)." (PMID 40401328, 2025). "Evidence supporting the prescription of ACE inhibitors/angiotensin II receptor blocker/angiotensin receptor and neprilysin inhibitor for patients with uncomplicated myocarditis is limited or absent." (PMID 38398340, 2024). "We advocate clinical studies investigating beta blockers and ACE inhibitors in patients presenting with myocarditis in the absence of LV dysfunction." (PMID 31673885, 2019). "According to the guidelines for the treatment of HF, beta-blockers and ACE inhibitors are indicated in patients with reduced LVEF, but the cardioprotective role of these drugs in preventing or mitigating ICI-related myocarditis has not yet been demonstrated." (PMID 36358830, 2022).